CNBP (CCHC-type zinc finger nucleic acid binding protein)
Diseases named in the same sentence as CNBP in open-access papers (continued):
Sharing a sentence is not in itself a finding about the gene and the disease.
gastric cancer (continued). "As a nuclear circRNA, circHuR interacts with CCHC-type zinc finger nucleic acid-binding protein (CNBP) and inhibits its binding to the HuR promoter, which ultimately down-regulates HuR and inhibits gastric cancer (GC) progression." (PMID 34445958, 2021). "Consistently, stable knockdown of circ-HuR increased the CNBP enrichment, promoter activity, transcripts and protein expression levels of HuR, MMP-14 and c-Myc in these gastric cancer cells, which were rescued by CRISPRi-mediated knockdown of CNBP." (PMID 31718709, 2019). "circHuR interacts with CNBP protein (CCHC-type zinc finger nucleic acid-binding protein) and inhibits the binding of CNBP to the HuR promoter, thereby leading to HuR down-regulation to further inhibit the proliferation, invasion and metastasis of gastric cancer cells." (PMID 33937077, 2021). "CircHuR inhibits gastric cancer (GC) proliferation, invasion and metastasis by sequestering CCHC-type zinc finger nucleic acid binding protein (CNBP) from the human antigen R (HuR) promoter, thus downregulating HuR and repressing tumor." (PMID 33317550, 2020).
Myotonia (7 papers, 2011 to 2024). An involuntary and painless delay in the relaxation of skeletal muscle following contraction or electrical stimulation. "Weakness was more often reported in individuals with dystrophic myotonia than non-dystrophic myotonia, with 90.8% (n = 79) of individuals with DMPK expansions and 90% (n = 9) with CNBP expansions reporting this as a symptom." (PMID 32670189, 2020).
breast cancer (5 papers, 2021 to 2024). A primary or metastatic malignant neoplasm involving the breast. "Based on this analysis, we report a novel observation of a significant increase in CNBP protein expression in matrix-deprived breast cancer cells." (PMID 37425300, 2023). "Additionally, immunoblotting of primary tumours from breast cancer patient samples showed increased levels of CNBP as compared to far away normal tissues." (PMID 37425300, 2023). "Furthermore, increased levels of CNBP were also obtained in matrix-deprived patient-derived breast cancer cells." (PMID 37425300, 2023).
viral infections (5 papers, 2021 to 2026). "As a readout of virus infection, we also monitored the accumulation of dsRNA using J2 antibody staining by immunofluorescence and found increased levels of J2 staining in CNBP-deficient cells." (PMID 37963251, 2023). "Emerging evidence implicates cellular nucleic acid-binding protein (CNBP), a zinc-finger transcriptional regulator, in control of IL12β gene expression in myeloid cells exposed to bacterial and viral infections." (PMID 42282833, 2026). "One of the RNA-binding proteins that host cells use to control viral infections is the RGG-containing motif cellular nucleic acid-binding protein (CNBP)." (PMID 38542351, 2024). "SARS-CoV-2 RNA G4s were found to be targeted and unwound by the cellular protein CNBP, disclosing new aspects in the virus/host interplay: since CNBP expression is enhanced in response to viral infections, the protein/G4 interaction could be targeted for antiviral purposes." (PMID 34681641, 2021). "Cells lacking CNBP or receptors for type I or type III IFNs have elevated viral loads, and animals lacking CNBP are more susceptible to virus infection than their wild-type counterparts." (PMID 37963251, 2023).
melanoma (4 papers, 2022 to 2025). A malignant, usually aggressive tumor composed of atypical, neoplastic melanocytes. "The expression of circTADA2A is significantly downregulated in melanoma cell lines and is positively associated with melanoma progression by interacting with CCHC-type zinc finger nucleic acid binding protein (CNBP) to influence the expression of solute carrier family 38 member 1 (SLC38A1)." (PMID 38635778, 2024). "Most interestingly, circTADA2A directly interacted with CNBP, and acted as an inhibitor to restrain the binding of CNBP to its downstream proteins, resulting in repression of melanoma cell progression." (PMID 38635778, 2024). "CircTADA2A inhibited melanoma growth and metastasis by interacting with CNBP protein to modulate gene transcription of SLC38A1." (PMID 38635778, 2024). "Taken together, these results showed that circTADA2A suppressed melanoma cell progression via repressing CNBP/ SLC38A1 pathway." (PMID 38635778, 2024). "Moreover, stable overexpression of circTADA2A attenuated the protein expression levels of SLC38A1 in melanoma cells, which were blocked by CNBP overexpression." (PMID 38635778, 2024). "In order to further investigate the interplay effects between circTADA2A and CNBP in regulating SLC38A1 expression and melanoma progression, A375 and A2058 cells were co-transfected with circTADA2A overexpression vector, CNBP overexpression vector and SLC38A1 knockdown vector." (PMID 38635778, 2024). "It is appealing to suspect that the circTADA2A/CNBP might also play essential roles in melanoma." (PMID 38635778, 2024). "Taken together, these results confirmed that circTADA2A could interact with CNBP in melanoma cells." (PMID 38635778, 2024). "CircTADA2A suppresses melanoma progression by regulating CNBP/SLC38A1 axis, indicating a potential therapeutic target in melanoma." (PMID 38635778, 2024). "Mechanistically, circTADA2A interacted with CNBP, acting to suppress the binding of CNBP to the SLC38A1 promoter and subsequently restrained SLC38A1 transcription, which resulting in repression of melanoma progression." (PMID 38635778, 2024).
muscular dystrophy (4 papers, 2012 to 2023). Muscular dystrophy (MD) refers to a group of more than 30 genetic diseases characterized by progressive weakness and degeneration of the skeletal muscles that control movement. "Although a CCTG expansion in the gene encoding the zinc knuckle protein CNBP causes a common form of muscular dystrophy, the function of both human CNBP and its putative budding yeast ortholog Gis2 remain poorly understood." (PMID 23285195, 2012).
cataract (3 papers, 2015 to 2023). Partial or complete opacity of the crystalline lens of one or both eyes that decreases visual acuity and eventually results in blindness. "Positive family history for core DM2 symptoms (proximal limb muscle weakness, presenile cataracts, and myotonia) was one of the main predictors of the CNBP gene mutation." (PMID 36401657, 2023). "On the contrary, Znf9+/– mice (lacking one CNBP allele) develop a multisystem phenotype resembling DM, including muscle wasting, heart failure and cataracts, which suggests that CNBP insufficiency may have a role in the pathologic mechanisms of DM2." (PMID 26217220, 2015).
hepatocellular carcinoma (3 papers, 2023 to 2025). A malignant tumor that arises from hepatocytes. "For example, circFMN2 contributes to sorafenib resistance in hepatocellular carcinoma via upregulation of CNBP by restraining ubiquitination." (PMID 38635778, 2024).
glioblastoma (2 papers, 2021 to 2022). The most malignant astrocytic tumor (WHO grade IV). "A similar ‘bind-unfold-lock’ mechanism was proposed for USP1 translational regulation by hnRNP H/F and DHX36 in glioblastoma or for the CNBP-targeted mRNAs." (PMID 36107769, 2022).
medulloblastoma (2 papers, 2018 to 2023). A malignant, invasive embryonal neoplasm arising from the cerebellum. "Together, these observations are in agreement with a pro-tumorigenic role for the SHH/AMPK/CNBP axis in medulloblastoma." (PMID 30360486, 2018). "Subsequently, the increased level of CNBP protein expression results in the increased translation of ODC1 and associated activation of polyamine metabolism, which is essential for the SHH-dependent proliferation of medulloblastoma cells." (PMID 30360486, 2018). "Moreover, we performed complementary molecular and genomic analyses that support the hypothesis of a pro-tumorigenic SHH/AMPK/CNBP axis in medulloblastoma." (PMID 30360486, 2018). "CNBP has both transcriptional and translational roles, notably acting as an ITAF (IRES Trans-Activating Factor) in medulloblastoma." (PMID 37425300, 2023). "We observed high copy numbers for the AMPK, CNBP, and ODC1 genes not only in SHH but also in Group #3 medulloblastoma." (PMID 30360486, 2018). "In conclusion, notwithstanding that other AMPK substrates may also contribute to the pro-tumorigenic role of AMPKα2 in medulloblastoma, these results further support the hypothesis of a critical role for the SHH/AMPK/CNBP axis in SHH-driven medulloblastoma." (PMID 30360486, 2018). "In other words, not only are AMPK, CNBP, and ODC1 genes frequently gained in medulloblastoma, but these gains tend to co-occur more often than expected at random, suggesting that the co-occurrence of these gains may provide a synergistic advantage." (PMID 30360486, 2018). "Similarly, in medulloblastoma, the role of AMPK as both an inhibitor of GLI1 and SHH signaling (tumor-suppressive effect) as well as a promoter of CNBP and polyamine metabolism (pro-tumorigenic effect) supposes a dual role for AMPK in this disease context." (PMID 30360486, 2018). "Taken together with the complementary report that both SHH and Group #3 medulloblastomas show a high level of expression of CNBP and ODC1 proteins, the SHH/AMPK/CNBP axis could then have a critical role in both the SHH and Group #3 subgroups." (PMID 30360486, 2018). "Interestingly, strong copy number gains are also observed for CNBP and ODC1 in SHH medulloblastoma (19% and 11%, respectively), as well as in Group #3 medulloblastoma (10% and 22%, respectively)." (PMID 30360486, 2018). "In agreement with the observation that CNBP protein levels are decreased in the absence of AMPKα2, we observed that the pro-tumorigenic function of AMPKα2 prevails in the context of the highly penetrant [GFAP-tTA;TRE-SMOA1] mouse model of medulloblastoma." (PMID 30360486, 2018).
neuroblastoma (2 papers, 2016 to 2023). Neuroblastoma (NB) is the most common solid, extracranial childhood tumor. "CNBP is associated with poor prognosis and clinical progression of neuroblastoma." (PMID 37186134, 2023). "Therapeutic targeting of phase separation and interaction of CNBP with SMARCC2 inhibits neuroblastoma progression." (PMID 37186134, 2023). "CNBP modulates SWI/SNF activity via SMARCC2 to drive ribosome biogenesis of neuroblastoma cells and subsequent M2 macrophage polarisation." (PMID 37186134, 2023).
Treacher-Collins syndrome (2 papers, 2016 to 2024). A congenital disorder of craniofacial development characterized by bilateral symmetrical oto-mandibular dysplasia without abnormalities of the extremities, and associated with several head and neck defects. "G4s as cis-acting elements and their modulation by CNBP may contribute in the complex regulatory network that orchestrate neural crest induction, migration, and colonization of pharyngeal arches and help to explain the variable expressivity of Treacher Collins Syndrome." (PMID 38553547, 2024).
AIDS (1 paper, 2022). A syndrome resulting from the acquired deficiency of cellular immunity caused by the human immunodeficiency virus (HIV). "This role of CNBP suggests an additional explanation in the pathogenesis of the wide variety of AIDs in DM2." (PMID 36468046, 2022).
asthma (1 paper, 2022). "Therefore, these genes can increase the odds and show an up-regulated effect on the outcome of asthma, while 40 genes including CNBP, POLL, ZNF696, HUS1 among others impose a down-regulated effect on the disease response." (PMID 35606385, 2022).
chondrosarcoma (1 paper, 2022). A malignant cartilaginous matrix-producing mesenchymal neoplasm arising from the bone and soft tissue. "GAPDH and other proteins whose secretion was augmented in response to hypoxia, including CNBP and SNRPA, could represent proteomic signatures of chondrosarcoma and could be developed as chondrosarcoma biomarkers." (PMID 35893766, 2022).
osteosarcoma (1 paper, 2024). A usually aggressive malignant bone-forming mesenchymal neoplasm, predominantly affecting adolescents and young adults. "In conclusion, our results revealed that circPRMT5 promotes osteosarcoma malignant activity by recruiting CNBP to facilitate the translation and stability of CDK6 mRNA." (PMID 38626179, 2024). "Mechanistically, circPRMT5 enhanced cyclin-dependent kinase 6 (CDK6) expression by promoting the binding of CCHC-type zinc finger nucleic acid binding protein (CNBP) to CDK6 mRNA in osteosarcoma cells." (PMID 38626179, 2024). "Mechanically, circPRMT5 promoted the binding of CNBP to CDK6 mRNA, which enhanced the stability of CDK6 mRNA and facilitated its translation, thereby promoting the progression of osteosarcoma." (PMID 38626179, 2024). "Together, these findings indicate that circPRMT5 may serve as an oncogenic factor to promote CNBP-facilitated CDK6 expression and osteosarcoma progression." (PMID 38626179, 2024).
pancreatic ductal adenocarcinoma (1 paper, 2022). An infiltrating adenocarcinoma that arises from the epithelial cells of the pancreas. "Mechanistically, increased WTAPP1 mRNA levels in pancreatic ductal adenocarcinoma are caused by m6A modification, which stabilizes WTAPP1 mRNA by recruiting the RNA stabilizer HuR by CCHC-type zinc finger nucleic-acid-binding protein (CNBP)." (PMID 36139062, 2022).
parasitemia (1 paper, 2026). "Mice lacking CNBP in hematopoietic stem cells exhibited changes in transcription of key inflammatory genes; markedly reduced systemic IL12β and IFN-γ, leading to significantly elevated peripheral blood parasitemia and altered immune cell composition." (PMID 42282833, 2026).
septic arthritis (1 paper, 2025). "In murine infection models, animals inoculated with a cnbP-deficient isogenic mutant exhibited a markedly reduced incidence of septic arthritis (27% vs. 70%), indicating that CnBP is a critical determinant of arthritogenic virulence and disease progression." (PMID 41170422, 2025).
uveal melanoma (1 paper, 2025). A melanoma derived from melanocytes of the uveal tract. "CNBP is located on chromosome 3, which is frequently lost in uveal melanoma." (PMID 39804140, 2025).
tumor (31 papers, 2007 to 2026). "Consistently, steady up‐ or down‐regulation of CNBP caused a significant increase or decrease in volume, weight, proliferative index and microvessel density of xenograft tumours generated by subcutaneous injection of SH‐SY5Y cells into nude mice." (PMID 37186134, 2023). "CNBP expression is elevated in human tumor tissues, and is associated with proliferation, invasion, and migration of tumor cells in vitro and in vivo." (PMID 31718709, 2019). "Notably, CNBP is closely associated with tumor occurrence and development." (PMID 38626179, 2024). "Circ-HuR binds to cellular nucleic acid-binding protein (CNBP) and inhibits the interaction between CNBP and the promoter region of the HuR gene, thus reducing HuR expression and tumor progression." (PMID 39199340, 2024). "For example, circHuR interacts with CCHC-type zinc finger nucleic acid binding protein (CNBP) and subsequently restrains its binding to HuR promoter, leading to repression of HuR expression and tumor progression." (PMID 39337606, 2024). "Additional investigation is necessary to elucidate the therapeutic effects of targeting CNBP/SMARCC2 in TH‐MYCN transgenic or immunocompetent mice, while quantitative proteomics are helpful in exploring additional CNBP protein partners in tumour progression." (PMID 37186134, 2023). "Overexpressed circ-HuR interacted with CNBP and inhibited its binding to the HuR promoter, further leading to a decline in HuR expression and suppression of tumor progression." (PMID 36732659, 2023). "Since immunohistochemical staining revealed the enrichment of F4/80+ M2 macrophages in subcutaneous xenograft tumours formed by CNBP over‐expressing NB cells, the impacts of CNBP or SMARCC2 on interplay between NB and macrophages were further explored." (PMID 37186134, 2023). "Herein, our results indicated that CNBP‐SMARCC2 condensates assembling through LLPS were essential for ribosome biogenesis in tumours." (PMID 37186134, 2023). "The expression levels of BAX (p = 0.0017), ERH (p = 0.0067), APC (p = 0.0416), and CNBP (p = 0.0244) were significantly higher in tumor tissues of the NBL group than in the control group." (PMID 35991559, 2022). "As a tumor suppressor, circ-HuR interacts with CCHC-type zinc finger nucleic acid-binding protein (CNBP) and therefore inhibits its binding to the human antigen R (HuR) promoter, leading to the downregulation of HuR." (PMID 35595755, 2022). "Particularly, a proteomic analysis was performed to suggest the binding of circ-HuR to CNBP arrested the function of CNBP on facilitating HuR expression and suppress tumor progression." (PMID 34335937, 2021). "circHuR, consisting of exons 3 to 5 of HuR, interacted with the RBP CCHC-type zinc finger nucleic acid binding protein (CNBP) and restrained its binding to HuR promoter, resulting in down-regulation of HuR and repression of tumor progression." (PMID 33537235, 2020). "CNBP overexpression enhanced glucose consumption and lactate production but decreased glycogen content of tumor cells." (PMID 30335765, 2018). "Interestingly, the downregulated gene CNBP by siSHMT2 can also control the tumor cell biology by regulating the expression of tumor-promoting genes by acting as a transcription factor." (PMID 41347062, 2025). "The circTADA2A/CNBP complex is likely to be located in the nucleus and may be required to regulate the transcription of genes involved in tumor progression." (PMID 38635778, 2024). "Consistent with previous studies, our findings suggested that CNBP may act as a mRNA chaperone and enhance the mRNA translation and stability, thus promoting tumor progression." (PMID 38626179, 2024). "In addition, CNBP is able to facilitate EV‐mediated delivery of 18S rRNA from tumour cells to monocytes, leading to M2 macrophage polarization." (PMID 37186134, 2023).